KLRK1 (killer cell lectin like receptor K1)
Description:
Functions as an activating and costimulatory receptor involved in immunosurveillance upon binding to various cellular stress-inducible ligands displayed at the surface of autologous tumor cells and virus-infected cells. Provides both stimulatory and costimulatory innate immune responses on activated killer (NK) cells, leading to cytotoxic activity. Acts as a costimulatory receptor for T-cell receptor (TCR) in CD8(+) T-cell-mediated adaptive immune responses by amplifying T-cell activation. Stimulates perforin-mediated elimination of ligand-expressing tumor cells. Signaling involves calcium influx, culminating in the expression of TNF. Participates in NK cell-mediated bone marrow graft rejection. May play a regulatory role in differentiation and survival of NK cells. Binds to ligands belonging to various subfamilies of MHC class I-related glycoproteins including MICA, MICB, RAET1E, RAET1G, RAET1L/ULBP6, ULBP1, ULBP2, ULBP3 (ULBP2>ULBP1>ULBP3) and ULBP4.
Synonyms: CD314; D12S2489E; NKG2D; KLR; NKG2-D
Tractability: Antibody: UniProt places it where antibodies can reach, with high confidence; its Gene Ontology location is reachable by antibodies, with high confidence; UniProt predicts a signal peptide or a membrane-spanning region; the Human Protein Atlas places it where antibodies can reach.
Gene: Protein-coding gene on chromosome 12 (10,372,353 to 10,391,874, reverse strand). Ensembl gene ENSG00000213809.
Subcellular location: Cell membrane
Subcellular location (Human Protein Atlas): Plasma membrane
Pathways (Reactome):
Immune System: DAP12 interactions; DAP12 signaling; Immunoregulatory interactions between a Lymphoid and a non-Lymphoid cell
Gene Ontology:
Molecular function: protein binding; signaling receptor activity; identical protein binding; MHC class I protein binding; MHC class Ib receptor activity
Biological process: natural killer cell mediated cytotoxicity; negative regulation of GTPase activity; negative regulation of natural killer cell chemotaxis; positive regulation of natural killer cell mediated cytotoxicity; natural killer cell activation; signal transduction; T cell costimulation; defense response; positive regulation of multicellular organismal process; response to other organism
Cellular component: cell surface; plasma membrane; external side of plasma membrane; membrane
Genetic constraint (gnomAD): Loss-of-function variants: 39 observed, 30.57 expected, observed/expected ratio (o/e) 1.28, 90% interval 0.99 to 1.66. The upper end of that interval is the gene's LOEUF score, 1.66, which puts it in group 6 of 6, group 1 being the genes least tolerant of losing a copy. Missense variants: 217 observed, 234.94 expected, observed/expected ratio (o/e) 0.92, 90% interval 0.83 to 1.03. Synonymous variants: 66 observed, 70.88 expected, observed/expected ratio (o/e) 0.93, 90% interval 0.76 to 1.14.
Homologues: Orthologues: chimpanzee KLRK1 (99% identical), macaque NKG2D (94% identical), dog KLRK1 (67% identical), pig KLRK1 (64% identical), rabbit KLRK1 (61% identical), mouse Klrk1 (59% identical), rat Klrk1 (59% identical), Caenorhabditis elegans clec-196 (13% identical). Paralogues in human: OLR1 (28% identical), CLEC9A (25% identical), CLEC12B (24% identical), CLEC7A (23% identical), CLEC12A (21% identical), CLEC1B (21% identical), KLRC1 (21% identical), KLRD1 (21% identical), KLRC2 (20% identical), CLEC1A (19% identical), KLRB1 (19% identical), KLRC3 (19% identical), and 11 more.
Diseases named in the same sentence as KLRK1 in open-access papers:
KLRK1 is named in the same sentence as 271 diseases in open-access papers, as found by Europe PMC text mining. Sharing a sentence is not in itself a finding about the gene and the disease. The quoted sentences say what the papers report.
melanoma (86 papers, 2009 to 2025). A malignant, usually aggressive tumor composed of atypical, neoplastic melanocytes. "Investigations have shown that miR-155 is involved in the functions of NK cells in melanoma by positively regulating Killer Cell Lectin Like Receptor K1 (KLRK1), interferon (IFN-γ), and granzyme B production." (PMID 36980512, 2023).
viral infection (77 papers, 2009 to 2026). "A prominent member of this group is NKG2D (KLRK1), an activating receptor that binds to several MHC class I-like molecules induced by various forms of cellular stress such as viral infection, tumor formation, tissue damage, and heat shock." (PMID 24223577, 2013).
breast cancer (54 papers, 2009 to 2025). A primary or metastatic malignant neoplasm involving the breast. "Furthermore, in breast cancer molecular subtypes, KLRB1 and KLRK1 were higher in TNBC and ER+/HER2+BC in contrast to ER+/HER2−BC." (PMID 38713229, 2024).
colorectal cancer (42 papers, 2008 to 2025). A primary or metastatic malignant neoplasm that affects the colon or rectum. "In keeping with this, the high expression of Klrk1 in the most immunogenic consensus molecular subtype 1 (CMS1) subtype of colorectal cancer has been linked to poorer survival." (PMID 37626965, 2023). "Moreover, increased KLRK1 (encoding NKG2D) expression was associated with decreased overall survival in colorectal cancer, suggesting that NKG2D reduces tumor control in certain human tumors." (PMID 40849493, 2025).
autoimmune disease (38 papers, 2011 to 2025). A disorder resulting from loss of function or tissue destruction of an organ or multiple organs, arising from humoral or cellular immune responses of the individual to their own tissue constituents. "A review of published reports demonstrates that polymorphisms in the KLRK1 gene influence the natural cytotoxic activity, predisposing to infectious diseases, cancers, autoimmune disorders, pregnancy miscarriages or transplant-related mortality." (PMID 34200375, 2021). "Klrk1 gene polymorphisms lead to infectious diseases, cancer, and autoimmune diseases." (PMID 36276964, 2022). "KLRK1 gene polymorphism may represent a potential biomarker for prediction of treatment outcome in patients with cancers, autoimmune diseases or virus induced diseases." (PMID 34200375, 2021).
prostate carcinoma (38 papers, 2010 to 2025). A carcinoma that arises from epithelial cells of the prostate gland. "NKG2D-deficient (Klrk1−/−) mice are more susceptible to the development of several types of primary tumors, such as a transgene-driven lymphoma and prostate carcinoma, and the overexpression of NKG2D ligands is protective in models of transplanted tumors." (PMID 33546248, 2021). "For example, TRAMP mice deficient in NKG2D/KLRK1, an NK cell receptor, develop more aggressive prostate cancer than their wild-type counterparts." (PMID 30692641, 2019).
lymphoma (36 papers, 2011 to 2025). A malignant (clonal) proliferation of B- lymphocytes or T- lymphocytes which involves the lymph nodes, bone marrow and/or extranodal sites. "showed, in 2008, that the deletion of Klrk1, the gene encoding NKG2D, in Eμ-Myc mice, accelerates the emergence of Eμ-Myc-induced lymphomas." (PMID 34113345, 2021). "Transcript levels of NKG2D (KLRK1) were reduced in MYCON lymphoma mice and restored to normal levels in MYCOFF mice, suggesting suppression of NKG2DL on MYC-driven lymphoblasts." (PMID 32503978, 2020).
cervical cancer (35 papers, 2008 to 2025). A primary or metastatic malignant neoplasm involving the cervix. "KLRK1 was thought to promote cervical cancer and CIN lesion susceptibility in 195 patients from southern Brazil." (PMID 34414195, 2021). "KLRK1 knockout mice develop prostate adenocarcinomas and B cell lymphomas, and polymorphisms in the KLRK1 gene are associated with the susceptibility of developing liver and cervix cancers." (PMID 27703456, 2016). "The expression of BTLA, KLRK1, CD80, and CD28 reduced the risk score, and these were suggested as protective factors in cervical cancer prognosis." (PMID 39312339, 2024). "Our group reported an association between the variant LNK, determined by the SNP rs1049174 in the 3′UTR region of KLRK1 gene (which encodes NKG2D receptor), with increased risk of HPV-induced cancers, including cervical cancer, anal cancer and vaginal cancer." (PMID 31337018, 2019).
lung carcinoma (33 papers, 2010 to 2025). "Similarly, we found the KLRK1 presented a promising diagnostic value in lung cancer, especially advanced stages." (PMID 35132098, 2022). "In comparison of lung cancer vs. tumor, the AUC could get into 0.789, indicating a relatively high diagnostic value of KLRK1 as a biomarker for lung cancer." (PMID 35132098, 2022). "Our research first suggested the diagnostic and prognostic value of KLRK1 for lung cancer." (PMID 35132098, 2022). "Moreover, KLRK1 presented a moderate diagnostic value for lung cancer." (PMID 35132098, 2022). "Studies have shown that KLRK1 activates NK cells and inhibits lung cancer proliferation and metastasis by controlling lung cancer through immune surveillance, thereby improving the prognosis, which is consistent with our findings." (PMID 39575432, 2024). "Of note, our results showed the significances of KLRK1 in both overall survival and relapse free survival in lung cancer." (PMID 35132098, 2022). "Lung cancer patients with high KLRK1 expression presented an improved overall survival (P = 0.0036) and relapse free survival (P = 0.0031)." (PMID 35132098, 2022). "In this bioinformatics study, KLRK1 was found to lower expressed in lung cancer compared with normal lung tissue." (PMID 35132098, 2022). "Their results confirmed the role of KLRK1 in changing state of NK cells, leading to the control of lung cancer through immunosurveillance." (PMID 35132098, 2022). "T classification (P < 0.001), N classification (P < 0.001), residual tumor (P = 0.016), stage (P < 0.001) and KLRK1 expression (P = 0.004) showed significant differences for lung cancer." (PMID 35132098, 2022). "We further studied the effect of KLRK1 on cells by overexpressing KLRK1 in lung cancer A549 cell lines." (PMID 35132098, 2022). "In conclusion, KLRK1 was lower expressed in lung cancer in comparison with normal lung tissue." (PMID 35132098, 2022). "Besides, in vivo function experiments and exploration of its molecular mechanism would further illuminate the role of KLRK1 in lung cancer." (PMID 35132098, 2022). "In this study, we first found KLRK1 as a prognostic biomarker for lung cancer." (PMID 35132098, 2022). "In this study, expression of KLRK1 in patients with lung cancer was first evaluated." (PMID 35132098, 2022). "However, there has not been one research of KLRK1 as a biomarker in lung cancer." (PMID 35132098, 2022).
COVID-19 (27 papers, 2021 to 2025). A disease caused by infection with severe acute respiratory syndrome coronavirus 2. "We demonstrated the downregulation of IFITM10, CH25H, NCR3, and KLRK1 and the upregulation of ID1 in the PBMCs from RTP patients compared with that from patients with moderate or severe COVID-19." (PMID 34687295, 2021).
sarcoma (15 papers, 2014 to 2024). A usually aggressive malignant neoplasm of the soft tissue or bone. "It was reported that the KLRK1 axis is becoming an emerging target in cancer immunotherapy, and the overexpression of CD226 or KLRK1 on NK cells resulted in efficient anti-sarcoma activity." (PMID 33549054, 2021). "NKG2D-mediated immunoediting was also reported in MCA-sarcoma models from mice lacking perforin (Prf1−/−) and in B cell tumors from NKG2D-deficient mice (Klrk1−/−)." (PMID 33546248, 2021).
diabetes (14 papers, 2012 to 2025). "In the current study, we compared effector CTL responses and diabetes development between NOD mice genetically deficient in NKG2D expression (Klrk1−/−) and wild-type NOD mice." (PMID 29497709, 2017). "The reduced diabetes development in Klrk1−/− NOD mice was inconsistent with our finding that NKG2D–H60a interaction decreases CTL effector function." (PMID 29497709, 2017). "By contrast, with antibiotic treatment, diabetes development was enhanced in Klrk1−/− compared with wild-type NOD mice." (PMID 29497709, 2017). "This corresponded with increased effector cytokine production by Klrk1−/− NOD CTL in vivo and increased diabetes development in microbiota-depleted Klrk1−/− NOD mice." (PMID 29497709, 2017). "By contrast, microbiota-replete Klrk1−/− mice had reduced diabetes development compared with wild-type mice, showing a separate effect resulting from interactions between NKG2D and the microbiota." (PMID 29497709, 2017). "To test this, we first compared diabetes development between Klrk1−/− and wild-type NOD littermates housed under SPF conditions." (PMID 29497709, 2017). "By contrast, diabetes development in Klrk1−/− mice was unchanged by antibiotic treatment." (PMID 29497709, 2017). "However, in both sexes, the Klrk1−/− mice exhibited slower diabetes development compared with wild-type mice." (PMID 29497709, 2017). "When we assessed diabetes incidence in Klrk1−/− and wild-type NOD mice, our results indicated a different effect of NKG2D genotype on diabetes incidence depending upon whether the mice were treated with microbiota-depleting antibiotics." (PMID 29497709, 2017).
B cell lymphoma (10 papers, 2014 to 2025). "A similar effect was shown on an EBV dependent mouse B-cell lymphoma, and also in a BL λ-Myc-Klrk1-/- mouse model." (PMID 34113345, 2021).
Hepatitis (9 papers, 2013 to 2025). Inflammation of the liver. "To study the role of NKG2D in Con A-induced hepatitis, we used Klrk1−/− mice deficient in NKG2D protein described in a previous study." (PMID 29868013, 2018). "Whereas all wild-type mice died between 15 to 20 h, 20% of Klrk1−/− mice died within this time frame, and 60% of them were still alive at 40 h, clearly demonstrating the less sensitivity of Klrk1−/− mice to Con A-induced hepatitis." (PMID 29868013, 2018).
lung adenocarcinoma (7 papers, 2015 to 2023). A carcinoma that arises from the lung and is characterized by the presence of malignant glandular epithelial cells. "Phase I/II lung adenocarcinoma (P = 0.0094), older patients (P = 0.0072), male (P = 0.0033), and KLRK1 were all found to have substantial predictive significance." (PMID 36874133, 2023). "In phase I/II lung adenocarcinoma tumor individuals (P = 0.0025) and older patients (P = 0.012), KLRK1 was found to have substantial predictive significance." (PMID 36874133, 2023). "By overall survival analysis of subgroups, KLRK1 was found to have significant prognostic value in lung adenocarcinoma (P = 0.015), stage I/II (P = 0.03), older patients (P = 0.0052), and male (P = 0.0047)." (PMID 35132098, 2022). "KLRK1 expression in lung squamous cell carcinoma was lower than that in lung adenocarcinoma (P = 2.2e−05)." (PMID 35132098, 2022). "By relapse free survival analysis of subgroups, KLRK1 was found to have significant prognostic value in lung adenocarcinoma (P = 0.0094), stage I/II (P = 0.0076), older patients (P = 0.0072), and male (P = 0.0033)." (PMID 35132098, 2022). "The roles of KLRK1 and RGL4 have not been investigated in any malignancies but have been identified as prognostic factors in lung adenocarcinoma." (PMID 35300417, 2022).
vitiligo (7 papers, 2012 to 2024). Generalized well circumscribed patches of leukoderma that are generally distributed over symmetric body locations and is due to autoimmune destruction of melanocytes. "KLRK1, encoding the activating NK cell receptor NKG2D and TRGC1 that encodes a T cell receptor γ-chain showed a tendency for increased expression in vitiligo lesional skin compared to that in healthy skin (p = 0.055 and p = 0.058, respectively)." (PMID 30515176, 2018).
Sepsis (6 papers, 2012 to 2024). Sepsis is defined as life-threatening organ dysfunction caused by a dysregulated host response to infection. "Comparing the overall interaction responses of the immune-related clusters CD177, GPR84, and KLRK1, stimulatory responses were observed between KLRK1 and its associated genes in adult sepsis, adult SIRS, pediatric SIRS and pediatric resolved SIRS." (PMID 32318053, 2020). "In pediatric sepsis there are again alterations in the complement of genes associated with each hub gene and significantly increased stimulatory interactions for nearly all hubs, with the exception of KLRK1 and PCOLCE2." (PMID 32318053, 2020). "The pattern is similar to that for pediatric sepsis with connections between nearly all hubs with the exception of KLRK1, SLC16A3, and MYL9." (PMID 32318053, 2020). "The interaction maps for the sepsis group show a similar pattern to those for SIRS, i.e., specific changes in the complement of genes associated with each hub gene and significantly increased stimulatory interactions for KLRK1, FGF13, and MYL9." (PMID 32318053, 2020). "In conclusion, the present study revealed an unbalanced immune response at the transcriptome level of sepsis and identified genes for potential biomarkers of sepsis, such as ITK, CD247, MMP9, CD3D, MMP8, KLRK1, and GZMK." (PMID 35190763, 2022).
asthma (5 papers, 2014 to 2022). "Concretely, KLRK1 encodes NKG2D, and aberrant expression of NKG2D ligands has been reported in sites of inflammation and in tissues undergoing autoimmune pathologies, including asthma." (PMID 32948203, 2020). "To test our findings that those specific lncRNAs and mRNAs probably associated to immune/inflammatory-related genes in asthma, we selected three lncRNA/mRNAs, including KLRK1, LINC02145, GUSBP2, which exhibits differential expression before and after treatment for the qRT-PCR." (PMID 32948203, 2020). "In addition to these four apoptosis-related genes (TRIO, PEA15, KLRK1, NDUFA13), we also found that the other genes in desensitization-treatment-related module exhibiting distinct degree of correlations to asthma via literature review." (PMID 32948203, 2020).
tuberculosis (4 papers, 2013 to 2023). A chronic, recurrent infection caused by the bacterium Mycobacterium tuberculosis. "NK cell lectin-like receptor K1 (KLRK1 or NKG2D), encoded by Klrk1 gene, is an activating receptor on natural killer (NK) and T cells to lyse M. tuberculosis-infected monocytes and alveolar macrophages, and a promising target for regulating CD8+ T cell-mediated protection against TB." (PMID 33575361, 2021).
dengue (3 papers, 2014 to 2022). "Two of the SNPs associated with severe dengue were located in the NK cell lectin-like receptor K1 gene (KLRK1)." (PMID 35267010, 2022). "Features of hyperinflammation are associated with dengue severity, including higher biomarkers, impaired NK cell function, and polymorphisms in NK cell cytolytic function genes (KLRK1 and PRF1)." (PMID 35267010, 2022).
psoriasis (3 papers, 2022 to 2025). An autoimmune condition characterized by red, well-delineated plaques with silvery scales that are usually on the extensor surfaces and scalp. "Some psoriasis loci showed a substantial single-tissue eQTL, primarily in the cardiovascular system (artery coronary: rs240993/KIAA1919, rs9808753/TMEM50B, heart left ventricle: rs11053802/KLRC4, heart left ventricle: rs11053802/KLRK1, rs5063/CLCN6, rs1050414/HLA-B, rs2778031/SPIN1)." (PMID 36320003, 2022).
cutaneous leishmaniasis (2 papers, 2020 to 2023). Leishmaniasis affecting the skin. "Using an RNAseq dataset of 21 skin biopsies from cutaneous leishmaniasis lesions and 7 from healthy individuals, we found that KLRK1, which encodes NKG2D, is enriched in lesions of patients compared to healthy skin." (PMID 37603573, 2023).
intestinal cancer (2 papers, 2023 to 2024). "In this study, we demonstrate that high expression of the NKG2D receptor enhances the production of IFNγ in a mouse model of intestinal cancer and that KLRK1 expression in primary CRC patients strongly correlates with the expression of genes associated with an IFNγ response." (PMID 36980678, 2023).
lung squamous cell carcinoma (2 papers, 2019 to 2022). "But no significances were found in lung squamous cell cancer patients with high KLRK1 expression." (PMID 35132098, 2022).
spondyloarthritis (2 papers, 2019 to 2022). "KLRK1 is an activator of NK cell cytotoxicity, and NK cells have been shown to have a greater cytotoxic activity in individuals with cLBP as well as spondyloarthritis." (PMID 35794661, 2022).